CD40 (CD40 molecule)
Diseases named in the same sentence as CD40 in open-access papers (continued):
Sharing a sentence is not in itself a finding about the gene and the disease.
colitis (continued). "A subset of E-cadherin + inflammatory DCs has been identified in an anti-CD40 colitis model." (PMID 25651850, 2015). "To investigate if the prevention of dysbiosis by I3C during colitis results in microbiota that promotes AhR or BD‐1 expression, we collected the colonic content microbiota from control, anti‐CD40‐induced colitis, and anti‐CD40+I3C treated mice, and cocultured with MC38 and Caco2 cells for 24 h." (PMID 40410944, 2025). "Also, I3C therapy significantly reduced these cytokines in anti‐CD40‐induced colitis mice." (PMID 40410944, 2025). "IL-23 production by cDCs may be protective in acute colitis models such as DSS-induced colitis, whereas IL-23 upregulation by CX3CR1+ macrophages exacerbates chronic colitis models, including those induced by IL-10 deficiency or anti-CD40 agonistic antibody injection." (PMID 39379604, 2024). "However, colitis developed in Il‐23−/−Rag−/− mice only after anti‐CD40 injection, indicating that IL‐22 plasmid injections alone do not cause colitis." (PMID 38363052, 2024). "While CD40/TNFRS5 is one of the TNF-α receptors involved in colitis associated to IL-1β production, no significant variation was found in TNFα, IL-6, and adiponectin expression levels between HL-ARA and HL + ARA groups compared with the mice fed the Std-ARA diet." (PMID 36558497, 2022). "Moreover, GPR15 expression was previously reported to direct Treg cells to the large intestine and defects in GPR15 led to increased susceptibility to colitis in a Citrobacter rodentium infection model and reduced suppression or rescue of inflammation in anti-CD40 and T cell transfer colitis models." (PMID 34017333, 2021). "However, excessive IL-22 can deteriorate CD40-induced colitis by enhancing neutrophil recruitment." (PMID 32403291, 2020). "In addition, it was shown with the TNBS colitis mouse model that disease may be prevented when blocking either IL-12 or CD40Ligand-CD40 interaction." (PMID 26241646, 2015). "Our analysis found that microbiota population from anti-CD40+I3C treated mice significantly increased the expression of AhR and BD1 compared to cells cocultured with bacterial population from colitis mice." (PMID 39894796, 2025). "To further corroborate the role of AhR activation, we used a potent AhR ligand, TCCD, to test its effect on anti‐CD40 and DSS ‐induced colitis mouse models." (PMID 40410944, 2025). "In dextran sulphate sodium-induced colitis models in Kunming male mice, G. lemaneiformis inhibited CCL-25 and CCR-9 levels, increased CD40 and TGF-β1 and modulated the gut microbiota, suggesting its use as a functional food for ulcerative colitis patients." (PMID 40077614, 2025). "In PBLs, the frequencies of CD40+ and CD80+ cells were significantly increased in DSS-treated ERAP1+/− mice (p < 0.01) and in sulfasalazine-treated ERAP1+/− colitis mice (p < 0.05) compared to ERAP1+/− healthy controls." (PMID 40977735, 2025). "Our findings show that Fn significantly upregulated CD40 expression in intestinal DCs and activated the NF-κB pathway, concomitant with exacerbated gut inflammation in a TNBS-induced murine colitis model." (PMID 41567217, 2025). "We, therefore, analyzed the various clinical parameters in anti-CD40-, DSS- and TNBS -induced colitis." (PMID 39894796, 2025). "In the present study, we found increased mRNA expression of genes related to inflammatory and immune responses, including Cd27 and Cd40, as well as the chemotactic receptor Ccr8, in MLB cells from colitis rats." (PMID 40331987, 2025). "Due to the fact that Paneth cells in the intestinal Lieberkühn’s crypt produce mouse α-defensins, we analyzed the expression of AhR and α-defensin 1 in IECs from control and mice with TNBS-, Anti-CD40-, and DSS-induced colitis." (PMID 39894796, 2025). "In this study, we showed that CD40+, CD83+, and CD80+ cells were decreased in IELs of colitis mice after probiotic mixture treatment." (PMID 39201260, 2024).
colitis (continued). "The probiotic mixture administered to mice with colitis reduced the frequencies of CD40+ (p < 0.001), CD83+ (p < 0.01), and CD80+ (p < 0.001) cells compared to untreated colitis mice." (PMID 39201260, 2024). "The interaction between CD40 and CD40L tends to play a crucial role in the pathogenesis of experimental colitis." (PMID 37242677, 2023). "Upon very early colitis onset, DC-LMP1/CD40 animals showed elevated serum IgG- as well as IgA-levels." (PMID 33550886, 2021). "As mice with spontaneous colitis have the propensity to develop antibody responses against commensal bacteria, we next set out to identify antibody specificities in DC-LMP1/CD40 mice." (PMID 33550886, 2021). "Our previous study showed that SSP inhibited expression of co-stimulatory molecules CD40/CD40L on DCs, and this limited the function of DCs in colitis." (PMID 32754049, 2020). "We also observed the upregulation of the CD40 receptor as well as the downstream products of CD40 activation, MCP-1, and PAI-1, within the colons of mice with DSS-induced colitis and subsequent MC-LR exposure." (PMID 32498446, 2020). "Taken together, CD40-signalling is involved in colitis and IBD and we show in the present study that the role for CD40-signaling in colitis depends on strain variations." (PMID 30653608, 2019). "Here the authors show that mice with constitutive CD11c-specific CD40-signalling have altered CD103+ dendritic cell migration, reduced iTreg cell induction, and fatal colitis." (PMID 28276457, 2017). "The purified protein was able to block the CD40 activated signaling in vitro and to decrease the symptom of DSS-induced colitis in vivo." (PMID 26809818, 2016). "The initial characterisation of the anti-CD40 model identified an influx of myeloid cells, particularly CD40+ MHC-II+ CD11chi DCs, in specific inflammatory foci within the tip of the villi of the proximal colon during colitis." (PMID 26780670, 2016). "However, microbiota from anti‐CD40+I3C treated mice significantly increased the expression of AhR and BD1 compared to cells cocultured with microbiota from colitis mice." (PMID 40410944, 2025). "We also found that lactobacillus, which plays a protective role against UC, was predominantly found in control mice as well as colitis+I3C mice but were lacking in anti‐CD40 colitis mice." (PMID 40410944, 2025). "Notably, CD40+ cell frequencies remained elevated in ERAP1+/− colitis mice even after sulfasalazine treatment, compared to WT colitis mice (p < 0.05)." (PMID 40977735, 2025). "Furthermore, ERAP1+/− colitis mice exhibited higher levels of CD40+, CD80+, and CD83+ cells compared to WT colitis mice." (PMID 40977735, 2025). "Notably, pharmacological inhibition of CD40 using TRAF-STOP not only effectively suppressed Fn-induced NF-κB activation and ameliorated colitis severity, but also restored immune balance by reducing Th17 cells and increasing Treg cells." (PMID 41567217, 2025). "The cellular mechanism of H. hepaticus induced innate colitis is not known, but anti-CD40 induces innate colitis by activating CD40 expressing antigen presenting cells (primarily dendritic cells) and can occur in germ-free mice." (PMID 38512959, 2024). "Our data show a substantial lack of morbidity and disease of Hh-free DC-LMP1/CD40 mice, indicating a crucial role for this microbe in disease initiation and outcome in CD40-mediated colitis." (PMID 33550886, 2021). "The activation of CD40 is believed to be important for IL-10+ Breg generation as part of cognate interactions with activated T cells, as B cells lacking CD40 are unable to inhibit T cell activation and to protect mice from EAE or colitis." (PMID 33995344, 2021). "Despite the role of NFAM1 in promoting CD40L-mediated activation, NFAM1-/- mice are not protected against development of anti-CD40 colitis." (PMID 35095847, 2021).
colitis (continued). "Taken together, Hh-free SPF mice do not show genotype-dependent changes in taxa composition, suggesting that the transgenic genetic background of DC-LMP1/CD40 mice is not sufficient to drive development of fatal colitis in the absence of Hh." (PMID 33550886, 2021). "However, mice treated with CD40 Ab had enhanced 7a,25-OHC production, which in turn promotes colitis through activating the migration of GPR183+ ILC3s and myeloid cells to inflammatory foci." (PMID 33193381, 2020). "As TLR9 besides other TLRs has been shown to synergize with CD40-signalling in B cells, it is theoretically possible that a strain-specific differential TLR-expression in DCs contributes to the different grades of colitis observed in this study." (PMID 30653608, 2019). "However, the Rag-/- colitis model is T cell-independent, which is in contrast to the DC-LMP1/CD40 colitis model of the present study, where B6DC-LMP1/CD40 mice do not develop colitis when bred to the Rag-/- background." (PMID 30653608, 2019). "Analysis of the DC phenotype in murine colitis has shown that colonic lamina propria mature DCs express higher levels of costimulatory molecules (CD40, CD80, and CD86) and increase productions of IL-12p40 and IL-23p19 upon CD40 ligation." (PMID 31886308, 2019). "DC-LMP1/CD40-mice develop colitis without further experimentally induced challenges or acute infections." (PMID 28276457, 2017). "The role of GM-CSF in anti-CD40 mediated systemic disease has been recently reported but effects on colitis were not assessed." (PMID 26780670, 2016). "Taken together, our results may highlight a novel aspect of IECs as a IL-17A-inducer in murine colitis, and that costimulatory molecules in IECs such as CD80/CD86 and CD40 may be a therapeutic target for colitis." (PMID 24255712, 2013). "Interestingly, in these experiments, when we treated mice with mBD‐1 antibodies, I3C was not able to attenuate anti‐CD40‐mediated colitis." (PMID 40410944, 2025). "Notably, CD40+ and CD11c+ cells were further elevated in sulfasalazine-treated ERAP1+/− colitis mice than in WT counterparts, indicating an altered immune response and potential dysregulation in antigen presentation under conditions of ERAP1 haploinsufficiency." (PMID 40977735, 2025). "For one, our in vitro experiments focused on the role of NFAM1 in monocytes, while there are multiple cell types that contribute to anti-CD40 colitis, not all of which may be impacted by NFAM1 deletion." (PMID 35095847, 2021). "By d40 p.i., Hh-infected DC-LMP1/CD40 mice, but not control littermates showed a strong increase in cells infiltrating the colonic LP as well as a shortened and thickened colon, indicating ongoing inflammation and colitis." (PMID 33550886, 2021). "Our data indicate that CD40-signalling in colitis is not a single on/off switch, but that additional determinants contribute to the control of the DC-iTreg axis in CD40-mediated colitis." (PMID 30653608, 2019). "Therefore, only B6DC-LMP1/CD40-mice showed all signs of inflammation and colitis as published previously, while neither F1 nor B/c mice developed colitis, nor did they show signs of inflammatory cytokine production." (PMID 30653608, 2019). "High CD40 expression by DCs was recently demonstrated as directly responsible for decreased frequency of tolerogenic CD103+ DCs and of the immunosuppressive RORγt+Helios− iTreg cells, and consequently exacerbated inflammatory Th1/Th17 responses, microbial dysbiosis and fatal colitis." (PMID 30873168, 2019). "While we find that IFNγ drives acute intestinal inflammation in the anti-CD40 colitis model in an innate lymphoid cell (ILC)-dependent manner, IFNγ secreted by both transferred CD4 T cells and/or cells of the lymphopenic Rag1−/− recipient mice was dispensable for CD4 T cell-mediated colitis." (PMID 29416538, 2018).
colitis (continued). "However, using Rag and IL-15 receptor double deficient mice that lack NK cells, we found, as previously reported, that NK cells were not required for the development of anti-CD40 mediated colitis." (PMID 26780670, 2016). "However, blockade of IL-17A failed to modify anti-CD40-induced systemic or intestinal disease, indicating that IL-17A is dispensable for development of acute colitis in this model." (PMID 26780670, 2016). "In addition, in a non-infectious colitis model in Rag2-/- mice, where CD40 stimulation induced innate immune cell-mediated colitis, adoptive transfer of Tregs from wild-type mice reduced colitis severity and tissue damage, but Tregs from Gpr15 KO mice failed to do so." (PMID 37457732, 2023). "Taken together, these data demonstrated that CRISPR/Cas9-induced ablation of CD40 expression could effectively protect animals from colitis induction, and more importantly, our in vivo CRISPR/Cas9-based platform could be used to characterize gene function in colitis pathogenesis." (PMID 32155151, 2020). "However, we have shown previously that Il23a and Il1b mRNA is not induced directly by the LMP1/CD40-transgene, but rather a secondary effect of inflammation, as in B6DC-LMP1/CD40-mice on the Rag-ko background, these cytokines are not present and mice do not develop colitis." (PMID 30653608, 2019). "To further validate these findings in vivo, we isolated LP cells and observed a significant increase in CD40+ DCs in Fn-treated mice, both with and without TNBS-induced colitis." (PMID 41567217, 2025). "When we compared the phenotype of Hh-pos and Hh-free animals at the age of 14 weeks, we observed neither macroscopic signs of colitis, nor elevated total cell numbers in the colonic LP of Hh-free DC-LMP1/CD40 animals." (PMID 33550886, 2021). "While in this latter model, colitis was not due to CD4 T cell priming as DCs lacked MHCII, in DC-LMP1/CD40-mice, MHCII is reduced but not absent." (PMID 30653608, 2019). "In the present study, the level of MHC-II was increased in DCs from the colitis mice without treatment along with over-expression of costimulatory molecules of DCs, including CD83, CD28, B7-DC, CD40, CD40 L, and TLR2." (PMID 27932984, 2016). "Furthermore, compared to control animals, the abundance of the Verrucomicrobiota phylum decreased steadily in mice with anti-CD40-induced colitis, whereas the Verrucomicroiota phylum did not change significantly in mice with DSS-induced colitis." (PMID 39894796, 2025). "This might be of relevance for the colitis model presented here, as the levels of IL-10 were significantly reduced in the colon of B6 DC-LMP1/CD40 mice, but not those of other backgrounds." (PMID 30653608, 2019).
lupus (86 papers, 2006 to 2026). "The importance of CD40 variations lies in their association with several autoimmune disorders, such as Systemic Lupus Erythematosus (SLE) and Rheumatoid Arthritis (RA), suggesting shared genetic and immunological dysregulation mechanisms." (PMID 39810445, 2025). "A previous meta-analysis found a significant association between the CD40 rs4810485 polymorphism and susceptibility to rheumatoid arthritis and systemic lupus erythematosus in European populations." (PMID 40843700, 2025). "Subgroup analysis for association of CD40 gene polymorphisms and lupus patients by clinical features and laboratory parameters was carried out." (PMID 33968033, 2021). "For example, CD40 polymorphisms, linked to increased CD40 proteins levels, are associated with a higher risk of developing systemic lupus erythematosus (SLE) and Graves’ disease." (PMID 33407802, 2021). "A certain allele of CD40 has been identified in association with the higher risk of systemic lupus erythematosus (SLE) in the polymorphism studies." (PMID 33297945, 2020). "In our studies, we found that elevation of the expression level of miR-1246 in lupus B cells could decrease the expression of EBF1 causing the downregulation of CD40, CD80, and CD86 which are co-stimulatory molecules required for full B cell activation and IgG secretion." (PMID 25789080, 2015). "Multiple anti-CD40L or anti-CD40 drugs have been developed to reduce the risk of thromboembolic complications, such as dapirolizumab pegol (CDP7657) and VIB4920 in lupus, diabetes, Sjogren disease, and other autoimmune diseases." (PMID 40332536, 2025). "Recently, imiquimod-induced lupus mice were found to have cognitive impairment, brain injury, and heightened expression of hippocampal microglia CD40 similar to those of MRL/lpr mice." (PMID 40507090, 2025). "Through selective activation by TNFR family receptors including BAFFR and CD40, B cell survival is enhanced, antibody class-switching increases, leading to autoreactive immune cells and lupus immunopathology." (PMID 40672954, 2025). "The role of CD40-activated DCs in lupus is further revealed via their contribution to B cell differentiation into Ab-producing plasma cells." (PMID 39404385, 2024). "Anti-CD40 Ab significantly reversed the upregulation of inflammatory genes and the downregulation of metabolic pathways observed in kidneys of lupus mice to levels in control mice." (PMID 39404385, 2024). "As to anti-CD40 mAb therapies, it also showed numerous benefits in the treatment of lupus in mice models." (PMID 39404385, 2024). "Regarding the effects of the MSC secretome on B cells in lupus patients, we observed a decrease in CD40 MFI and a reduced percentage of CD19+PD-1+ and CD19+HLA-DR+ cells." (PMID 39684227, 2024). "CD40 is a costimulatory protein found on antigen-presenting cells (among which are especially B cells in lupus)." (PMID 34744730, 2021). "Activation of CD40 signaling was revealed to exacerbate autoimmunity and contribute to renal injury in the setting of systemic lupus erythematosus (SLE)." (PMID 33202988, 2020). "A recent study observed beneficial effects in a mouse model for systemic lupus erythematosus in which CD40 blockade by an antagonizing antibody reduced proteinuria in lupus nephritis." (PMID 33198327, 2020). "The current study demonstrated the specific stimulatory effects of hCG on the expression of CD40 and CD86 on B cells derived from lupus-prone mice, in conjunction with two TLR ligands, both of which have been implicated in lupus." (PMID 30574119, 2018). "The functional ex vivo assays showing increased frequencies of IL-10-producing B cells in Cd38−/− splenocytes than in WT upon stimulation with an agonist anti-CD40 mAb are in agreement with the in vivo experiments in the pristane-induced lupus model." (PMID 30257456, 2018).